NOD1 (nucleotide binding oligomerization domain containing 1)
Diseases named in the same sentence as NOD1 in open-access papers (continued):
Sharing a sentence is not in itself a finding about the gene and the disease.
acute kidney injury (2 papers, 2018 to 2024). Sudden and sustained deterioration of the kidney function characterized by decreased glomerular filtration rate, increased serum creatinine or oliguria. "It is known that NOD1 and NOD2 contribute to the pathogenesis of various inflammatory diseases, including acute kidney injury." (PMID 29609537, 2018).
atrophic gastritis (2 papers, 2011 to 2022). "NOD1 796G > A polymorphism is linked to gastric mucosal inflammation in H. pylori-infected Korean population, while NOD1 796A/A genotype increases risk of gastric atrophy and antral intestinal metaplasia in a Turkish population." (PMID 35547123, 2022). "A recent study from Turkey found that subjects with NOD1 796A/A genotype had a significantly increased risk for gastric atrophy and antral intestinal metaplasia with very high odds ratios, 34.2 and 39.7 respectively." (PMID 21864388, 2011). "We observed a tendency for NOD1 796G/G genotype for increased risk of atrophic gastritis (62.4% vs. 54.5% in controls, p = 0.082)." (PMID 21864388, 2011).
bacteremia (2 papers, 2012 to 2025). "This suggests that the NOD1 pathway might exert more selective effects on the vasculature than TLR4 during bacterial sepsis and that the capacity to pharmacologically differentiate the signalling pathways of these receptors in models of vascular inflammation may be instructive." (PMID 22870324, 2012).
breast tumor (2 papers, 2024). "To further explore the potential synergy among DTX, NOD1 inhibition, and ETBF clearance in ETBF-independent breast tumors, we established an ETBF colonized allograft mouse model with 4T1 cells." (PMID 38437016, 2024). "Some studies suggest that NOD1 activation primarily contributes to tumor suppression, particularly through the RIP2/TAK1/MAPK pathway-mediated apoptosis of breast tumor growth." (PMID 38462600, 2024).
Chagas disease (2 papers, 2013 to 2021). A parasitic infection caused by Trypanosoma cruzi. "According to these known information, DEGs (CASP2, CASP8, NOD1, MYD88, TLRs, IL-1s, NAIPs) involved in Chagas disease here are screened, which have been proven to be correlated with the activation or inhibition of multiple Chagas disease related pathways." (PMID 34171992, 2021). "We identified the candidate genes and pathways related to Chagas disease for resisting T. cruzi, it is found that CASP2, CASP8, NOD1, MYD88, TLRs, IL-1s, NAIPs, etc, would be responsible for the T. cruzi infection." (PMID 34171992, 2021). "Nod1-deficient mice are more susceptible to infection with Trypanosoma cruzi, the etiological agent of Chagas disease, apparently due to the lack of a robust nitric oxide production, suggesting that Nod1 may be involved in PG-independent microbial sensing given that T. cruzi does not express PG." (PMID 24273538, 2013).
chronic gastritis (2 papers, 2017 to 2025). Inflammation of the stomach that is chronic in nature. "Taken together, our results indicate that the sequential activation of TIFA, NOD1, and CagA delivery drives the initial inflammatory response in gastric epithelial cells, orchestrating the subsequent recruitment of immune cells and leading to chronic gastritis." (PMID 28811347, 2017).
E. coli infection (2 papers, 2012 to 2022). "It has been documented that murine norovirus-1 activates NOD1 and NOD2 signaling, which can accelerate the secondary E. coli infection." (PMID 35873172, 2022). "Nod-like receptor NOD1 in Caco-2 cells could prevent IκB kinase and NF-κB activation in response to enteroinvasive E. coli infection, whereas NOD2 is likely not important in signalling the onset of NF-κB activation." (PMID 22848393, 2012).
ear infection (2 papers, 2016 to 2022). A viral or bacterial infection that affects the external, middle, or inner ear. "The expression of NOD1 mRNA was lower in the otitis-prone group than in the non-otitis-prone group (p < 0.05), suggesting that the decrease in the expression of NLR mRNAs is related to the recurrence of OME." (PMID 35216465, 2022).
endotoxemia (2 papers, 2014 to 2017). "An important future goal is to understand divergence in Nod1 versus Nod2-induced metabolic effects and how these interact with endotoxemia." (PMID 28484277, 2017).
fetal growth restriction (2 papers, 2022). A fetus that does not grow beyond the 10th percentile of conventionally accepted weight for gestational age. "Increasing the level of NOD1 protein results in a higher level of inflammatory mediator that contributes to the development of intrauterine growth restriction." (PMID 36560538, 2022). "Furthermore, administration of FK565 induces a higher expression level of NOD1 in fetal vascular tissues and at the maternal–fetal interface, which result in intrauterine fetal growth restriction (IUGR) and death in pregnant mice." (PMID 36496806, 2022).
Hepatic steatosis (2 papers, 2020 to 2024). Steatosis is a term used to denote lipid accumulation within hepatocytes. "Compared to a control diet, feeding a high-fat diet (HFD) increased body weight gain, body fat percentage, and hepatic steatosis to a similar extent in female Nod1−/− and wild-type (WT) mice." (PMID 39507249, 2024).
infertile (2 papers, 2009 to 2024). "By investigating specific inflammasome-related polymorphisms, NOD1, and PYDC2 gene variants, we have uncovered potential associations with infertility and gastrointestinal complaints in affected individuals." (PMID 40034240, 2024). "In Period 2, both fertile and infertile animals expressed similar levels of the TLRs 1 to 10 and NOD1." (PMID 19476661, 2009).
ischemia (2 papers, 2018 to 2020). A hypoperfusion of the BLOOD through an organ or tissue caused by a PATHOLOGIC CONSTRICTION or obstruction of its BLOOD VESSELS, or an absence of BLOOD CIRCULATION. "However, in addition to sensing peptidoglycan, some studies have demonstrated that NOD1 expressed at a low level in stable conditions can be strongly upregulated in liver in response to ischemia and in mesangial cells following exposure to high glucose and LPS." (PMID 33261639, 2020).
leptospirosis (2 papers, 2017 to 2022). A contagious bacterial infection caused by spirochetes of the genus Leptospira. "Human/bovine TLR5 and human NOD1 might therefore play a specific role during acute leptospirosis in a susceptible host, considering that they can sense released agonists upon bacterial degradation." (PMID 35937697, 2022).
malaria (2 papers, 2013 to 2018). Malaria is a serious and sometimes fatal disease caused by a parasite that commonly infects a certain type of mosquito which feeds on humans. "The SNP rs2075820 in the NOD1 gene was previously reported as a polymorphism associated with clinical malaria in Mali." (PMID 30558622, 2018). "For clinical malaria, only significant associations were found in the Fulani (rs17047661 (CR1), OR 5.327, 95% CI 1.733-16.376, P=0.0008; rs2075820 (NOD1), OR 0.364, 95% CI 0.188-0.704, P=0.001)." (PMID 24098393, 2013).
mastitis (2 papers, 2012 to 2025). Inflammation of breast tissue during lactation or postpartum due to an obstructed duct or infection. "Nevertheless, during the course of mastitis, it is possible that peptidoglycan fragments recognized by NOD1 can reach the cytoplasm of bovine cells following invasion of epithelial cells by E. coli." (PMID 22330199, 2012).
myocardial infarction (2 papers, 2015 to 2018). Gross necrosis of the myocardium, as a result of interruption of the blood supply to the area, as in coronary thrombosis. "Ca2+ dynamics were examined before and after isoproterenol perfusion in cardiomyocytes isolated from healthy and from post-myocardial infarction (PMI) wild-type (WT) and Nod1-/- mice." (PMID 29962957, 2018). "For example, miR-1 has been reported to be downregulated in various CVDs including myocardial infarction (MI), and it is predicted to target multiple NLR proteins (NOD1, NLRP14, and NAIP)." (PMID 26491223, 2015).
peptic ulcer disease (2 papers, 2011 to 2014). A digestive system disease characterized by discontinuation in the inner lining of the gastrointestinal (GI) tract because of gastric acid secretion or pepsin. "Polymorphisms in NOD1 have been less extensively studied but the E266K SNP has been linked to an increased risk of peptic ulceration in patients infected with Helicobacter Pylori." (PMID 24598002, 2014). "Gene polymorphism 796G>A of NOD1 has been linked with peptic ulcer disease in H. pylori-positive patients and a significant association with very high odds ratios has been recently reported for the risk of premalignant lesions in the antrum of the stomach." (PMID 21864388, 2011).
renal fibrosis (2 papers, 2014 to 2018). A final common manifestation of a wide variety of chronic kidney diseases characterized by glomerulosclerosis and tubulointerstitial fibrosis. "However, infected kidneys from Nod1/2dko mice exhibited interstitial fibrosis, therefore excluding a role for both Nod1 and Nod2 in the induction of renal fibrosis." (PMID 24498450, 2014). "However, enhanced macrophage accumulation did not affect the progression of renal fibrosis in NOD1/2 DKO mice." (PMID 29609537, 2018). "Compared to infected WT mice, no reduction in Leptospira-induced fibrosis was observed in kidneys of either Nod1/2dko or Casp1ko mice, showing that Nod1, Nod2 and NLRP3 are not involved in the Leptospira-induced renal fibrosis." (PMID 24498450, 2014). "Since TLRs seem not to be involved in Leptospira-induced renal fibrosis, we wondered whether other innate immune receptors from the NLR family, such as the cytosolic Nod1, Nod2, and NLR3 receptors, could be involved." (PMID 24498450, 2014).
steatosis (2 papers, 2020 to 2022). Increased lipid within the cytoplasm of cells. "Interestingly, WT mice fed a HFD for 4 weeks followed by 2 weeks on CHD fully recovered from the lipid accumulation in liver, whereas NOD1 KO mice under the same nutritional protocol still exhibited clear signs of steatosis and lipid accumulation in the liver." (PMID 32704052, 2020). "Similarly, administration of NOD1 and NOD2 ligands exacerbated and improved steatosis, respectively." (PMID 36268029, 2022). "In addition to eWAT, the liver from NOD1 KO mice under HFD presented a significant steatosis, without elevation of serum transaminases except for a modest, although statistically significant increase in alanine aminotransferase (ALT)." (PMID 32704052, 2020).
streptococcal pneumonia (2 papers, 2011 to 2013). A febrile disease caused by streptococcus pneumoniae. "In addition to TLRs, Pseudomonas aeruginosa and Streptococcal pneumonia can also be recognized by NOD1 and NOD2, respectively." (PMID 21886831, 2011).
Stroke (2 papers, 2016 to 2023). Sudden impairment of blood flow to a part of the brain due to occlusion or rupture of an artery to the brain. "In humans, a previous study found the NOD1 rs5743336 polymorphism to be significantly more common in stroke patients seropositive for Chlamydia pneumonia compared to controls seropositive for Chlamydia pneumonia." (PMID 27936005, 2016).
vasculitis (2 papers, 2018 to 2025). "These three models, each utilizing distinct ligands and pattern recognition receptors (PRRs) such as Dectin‐2, Tlr2, and Nod1, may underscore the diversity of vasculitis‐inducing pathways in KD." (PMID 41017238, 2025).
acute liver failure (1 paper, 2021). Rapid deterioration of liver function causing encephalopathy and coagulopathy. "In the present study, we analyzed the effect of NOD1 agonist pretreatment on acute liver failure induced by lipopolysaccharide (LPS) in D-galactosamine (D-GalN)-sensitized mice." (PMID 33746949, 2021).
allergic asthma (1 paper, 2024). A asthma with a basis in a pathological type I hypersensitivity reaction. "Yahia (2021) found that deletion of NOD1 or RIPK2, but not NOD2, inhibited both BAL inflammation and airway responsiveness in response to methacholine in house dust mite (HDM)-induced allergic asthma in mice." (PMID 39507249, 2024).
allergic disease (1 paper, 2018). An immune response that occurs following re-exposure to an innocuous antigen, and that requires the presence of existing antibodies against that antigen. "Genetic variation in Nod1 is associated with susceptibility to several inflammatory disorders including allergic diseases and Crohn’s disease." (PMID 29679058, 2018).
autonomic neuropathy (1 paper, 2022). An inherited or acquired peripheral neuropathy affecting the autonomic nervous system. "Inhibition of NOD1 ameliorated PGN-induced bone marrow autonomic neuropathy, which significantly rejuvenated the HSPC pools and functions in vivo." (PMID 35966130, 2022). "Our data further showed that autonomic neuropathy underlies the PGN-mediated impairment of HSPC quantity and function and that bone marrow denervation relies on the nucleotide-binding oligomerization domain-containing protein 1- (NOD1-) dependent pathway." (PMID 35966130, 2022).
bacterial meningitis (1 paper, 2012). Inflammation of the membranes surrounding the brain and spinal cord due to a bacterial infection. "Eleven SNPs in seven genes (TLR2, TLR4, TLR9, NOD1, NOD2, CASP1, and TRAIL) were genotyped in 393 survivors of childhood bacterial meningitis (BM) (327 MM patients and 66 PM patients)." (PMID 22662111, 2012).
bladder cancer (1 paper, 2024). "Although NOD1 gene polymorphisms are associated with an altered risk of bladder cancer, the precise role of NOD1 in bladder cancer and its detailed molecular mechanisms remain unclear." (PMID 38462600, 2024). "Our study demonstrates that MARCH7 effectively suppresses the stem-like capacities of bladder cancer cells by interacting with NOD1." (PMID 38462600, 2024). "The overexpressed MARCH7 counteracts the effects of NOD1 on bladder cancer CSCs in both in vivo and in vitro models." (PMID 38462600, 2024). "In our investigation, we found that NOD1 promoted the stemness of bladder cancer cells, and MARCH7 overexpression abolished the stemness-inducing effects of NOD1." (PMID 38462600, 2024). "Consequently, MARCH7 and NOD1 have the potential to serve as clinical markers for prognostic evaluation in bladder cancer patients." (PMID 38462600, 2024). "Targeting the MARCH7/NOD1 pathway could be a promising therapeutic strategy for bladder cancer patients." (PMID 38462600, 2024). "Furthermore, our data indicated that NOD1 activates the NF-κB pathway in bladder cancer cells, consistent with previous reports." (PMID 38462600, 2024). "Given the direct interaction between MARCH7 and NOD1, we investigated the roles of the MARCH7/NOD1 axis in bladder cancer cells." (PMID 38462600, 2024). "Intriguingly, while NOD1 and NOD2 often function synergistically in various cellular mechanisms, our study revealed that MARCH7 exclusively interacted with NOD1 and not NOD2 in bladder cancer cells." (PMID 38462600, 2024).
bladder tumors (1 paper, 2024). "Our findings indicate that MARCH7 functions as a tumor suppressor and inhibits the stem-like capacities of bladder tumor cells by promoting the ubiquitin–proteasome degradation of NOD1." (PMID 38462600, 2024). "The overexpression of NOD1 significantly promoted bladder tumor growth." (PMID 38462600, 2024). "Additionally, immunohistochemistry staining revealed a significant negative correlation between MARCH7 expression and NOD1 levels in bladder tumors." (PMID 38462600, 2024).
breast adenocarcinoma (1 paper, 2025). "Mutations in the NOD1/2 signaling pathway and DNA binding transcription factor activity tended to happen late in breast adenocarcinoma and ovarian adenocarcinoma." (PMID 39868264, 2025). "Mutations in the NOD1/2 signaling pathway and in DNA binding transcription factor activity, affecting genes such as MAP3K7, UBE2N, IKBKG, CHUK, and IKBKB, occurred late in breast adenocarcinoma and ovarian adenocarcinoma." (PMID 39868264, 2025).
Cachexia (1 paper, 2023). Severe weight loss, wasting of muscle, loss of appetite, and general debility related to a chronic disease. "We also observed that Caspase 1 gene expression increased in terminal cachexia, whereas Nod2 gene expression was increased only on T7, returning to basal levels in T14, whereas Nod1 and Hif‐1α gene expression did not change during the development of cachexia." (PMID 37177862, 2023).
cholesteatoma (1 paper, 2015). A pathologic process characterized by the proliferation of keratinizing squamous epithelium resulting in the accumulation of keratin and cells in the middle ear and/or mastoid. "Immunohistochemistry demonstrated that, while only NOD2 was enhanced in cholesteatoma compared to EAS, both NOD1 and NOD2 are present in cholesteatoma." (PMID 25922834, 2015). "NOD1 and many proapoptotic caspase genes such as CASP1, CASP2, CASP8, and CASP9 were not altered in cholesteatoma." (PMID 25922834, 2015). "Microarray analysis showed significant upregulation for NOD2, not for NOD1, TLR2, or TLR4 in cholesteatoma." (PMID 25922834, 2015). "Thus, the nature of NLR signaling in cholesteatoma, with enhancement of NOD2 but not NOD1 expression, may contribute to the progressive and invasive nature of this disease." (PMID 25922834, 2015).
clear cell renal carcinoma (1 paper, 2023). A malignant epithelial neoplasm of the kidney characterized by the presence of lipid-containing clear cells within a vascular network. "On the other hand, NOD-1 expression levels were found to be lower in clear cell renal carcinoma compared to healthy tissue, posing the question as to whether this gene acts as a proto-oncogene or has tumor-suppressing capacity." (PMID 37624039, 2023).
clostridium difficile infection (1 paper, 2014). Symptomatic infection due to the spore-forming bacterium clostridium difficile. "Nod1-/- mice were also shown to exhibit impaired production of CXCL1 and defective recruitment of neutrophils to the intestine after Clostridium difficile infection, suggesting that NOD1-mediated neutrophil recruitment regulates susceptibility towards C. difficile in the intestine." (PMID 24479879, 2014).
co-infection (1 paper, 2014). "NOD1-deficient mice have an impaired ability to eliminate pulmonary Legionella pneumophila and to recruit neutrophils to the lungs; clearance of Streptococcus pneumoniae and Haemophilus influenzae also occurs via a NOD1-dependent manner in a murine model of co-infection." (PMID 25253572, 2014).
colorectal adenocarcinoma (1 paper, 2020). The most common type of colorectal carcinoma. "In order to confirm the presence of NOD1 in primary human CRC, immunohistochemistry (IHC) was carried out on tissue microarrays (TMA) of colorectal adenocarcinomas of both early and advanced stages probing for NOD1." (PMID 31956962, 2020).
cutaneous squamous cell carcinoma (1 paper, 2025). "Previous studies have identified the NOD1/2-NF-κb/ERK and IL−8 signaling axis as a potential driver of cancer progression in cutaneous squamous cell carcinoma, suggesting similar mechanisms may operate in GBM." (PMID 40868292, 2025).
cystic fibrosis (1 paper, 2014). Autosomal recessive disorder caused by pathogenic variants in the CFTR gene (cystic fibrosis transmembrane conductance regulator), which encodes a chloride and bicarbonate channel expressed in epithelial cells, and follow the diagnosis criteria. "Likewise it was demonstrated that NOD1 but not NOD2, seems to play a role in chronic infection of airway by P. aeruginosa in cystic fibrosis patients." (PMID 25433669, 2014).
dengue (1 paper, 2020). "Though NOD1 and NOD2 members of the NLR family are activated by specific bacterial peptides, similar to dengue and RSV, we report HEV-induced NLR activation." (PMID 32012176, 2020).